BRCA2 (BRCA2 DNA repair associated)
Diseases named in the same sentence as BRCA2 in open-access papers (continued):
Sharing a sentence is not in itself a finding about the gene and the disease.
ovarian carcinoma (continued). "An analysis of the presence of mutations in BRCA1, BRCA2, RAD51C, PALB2, and CHEK2 with the age of onset of ovarian cancer revealed a lower age of ovarian cancer diagnosis in BRCA1 mutation carriers than in non-carriers of BRCA1 (51.6 vs. 57.6, p = 2.97 × 10−11)." (PMID 33670479, 2021). "The common germline mutations in ovarian cancer includes BRCA1, BRCA2, ATM, MSH3 and PALB257." (PMID 33432021, 2021). "The genetic basis for ovarian cancer predisposition was originally established with the identification of BRCA1 (OMIM# 113705) and BRCA2 (OMIM# 600185), which are both tumor suppressor genes implicated in the mechanism of Homologous Recombination (HR) repair of DNA double-strand breaks." (PMID 34898566, 2021). "Although the mutations of BRCA1 and BRCA2 are the most common germline mutations in ovarian cancer, the mutational frequency of BRCA1 is significantly higher in Chinese than in Western (P = 0.0001), while the mutation frequency of BRCA2 is similar between them (P = 0.78)." (PMID 33432021, 2021). "Homozygous mutations in FANCD1/BRCA2 are associated with FA disease, while inherited heterozygous mutations in FANCD1/BRCA2 are associated with an increased risk of developing breast and ovarian cancers." (PMID 34830134, 2021). "BRCA1 or BRCA2 mutations are the most prevalent cause of high penetrance inherited breast or ovarian cancers and have been shown to affect patients irrespective of race or ethnicity." (PMID 33669749, 2021). "However, the penetrance of the BRCA1 or BRCA2 gene for ovarian cancer has been reported to be about 40% and 20%, respectively." (PMID 34356066, 2021). "There was a lower prevalence of ovarian cancer in the family for BRCA2 carriers (27.7%; 2202/7940)." (PMID 33926482, 2021). "This could explain why some families with an identical segregating BRCA2 mutation develop either predominantly PDAC or breast and ovarian cancer, and why some patients develop either one tumor type or even both." (PMID 34357098, 2021). "Finally, we perform complementation studies in immortalized human MCF10A breast epithelial and FTSEC (fallopian tube secretory epithelial) cells, relevant to breast and ovarian cancer, respectively, in which we have introduced an inducible shRNA against BRCA2." (PMID 34065235, 2021). "One of 4 tested BRCA2 mutations was found in 15 out of 2095 (0.72%) unselected ovarian cancer patients but in none of 1743 controls, and was associated with odds ratio 26.0 (95% CI: 1.55–434.8; p = 0.001)." (PMID 33670479, 2021). "We show significant correlation of mutations in BRCA1, BRCA2, and RAD51C with ovarian cancer risk." (PMID 33670479, 2021). "Interestingly, the cumulative risks of breast or ovarian cancer for Korean BRCA1 or BRCA2 carriers by region of BCCR or OCCR showed a different trend than what was previously reported." (PMID 34063308, 2021). "In the second functional network, the hub gene EMSY is an oncogene linking the BRCA2 pathway to sporadic breast and ovarian cancer and is involved in several cancer related biological processes like DNA damage, DNA repair, transcription and transcription regulation." (PMID 34752449, 2021). "BRCA2 (TI), whose biallelic loss is associated to responsiveness to PARP inhibitors and diagnostic relevance with evidence level I, as well as prognostic implications, was altered in 2 out of 10 ovarian cancer patients." (PMID 33947144, 2021). "Furthermore, the relative risk of ovarian cancer associated with RAD51C and RAD51D was comparable to BRCA2, with odds ratios for all three genes of approximately five." (PMID 33926482, 2021). "Employing next-generation sequencing, BRCA2 c.7795G>T, p.(Glu2599Ter) was detected in 78% of reads in DNA extracted from ovarian cancer tissue and 25% of reads in DNA derived from peripheral blood, which differs significantly from the expected 50% of a hereditary mutation." (PMID 34068254, 2021).
ovarian carcinoma (continued). "The ovarian cancer risk was associated with mutations in BRCA1 (OR = 40.79, 95% CI: 18.67–114.78; p = 0.29 × 10−15), in BRCA2 (OR = 25.98; 95% CI: 1.55–434.8; p = 0.001), in RAD51C (OR = 6.28; 95% CI 1.77–39.9; p = 0.02), and in PALB2 (OR 3.34; 95% CI: 1.06–14.68; p = 0.06)." (PMID 33670479, 2021). "BRCA1 and BRCA2 have key roles in the development of breast/ovarian cancer." (PMID 33726785, 2021). "The clinical condition of the two families was consistent with hereditary breast and/or ovarian cancer (HBOC) but they lacked pathogenic BRCA1 or BRCA2 variants." (PMID 34638292, 2021). "However, even if having a BRCA mutation is a well-known risk factor, among individuals with OC (ovarian cancer), both BRCA1 and BRCA2-associated patients have better outcomes." (PMID 33435590, 2021). "Rare variants in several genes that were initially implicated in risk for breast or ovarian cancer predisposition (e.g., BRCA1, BRCA2, CHEK2, BRIP1, and ATM), as well as the mismatch repair (MMR) genes, have also been reported to increase the risk of prostate cancer." (PMID 33804961, 2021). "Some clinicians may not be aware of the germline associations of specific ovarian cancer histologies and may choose to offer BRCA1 and BRCA2 testing only, even in the context of non‐serous, non‐mucinous ovarian cancer." (PMID 33369189, 2021). "For these reasons, we assumed that the patterns and effects of BRCA1 or BRCA2 pathogenic variants related to breast or ovarian cancer in Korean are different than those of other populations (not only non-Europeans but also other Asians)." (PMID 34063308, 2021). "To show the power of our approach, we used it to compare the BRCA2 mutational status of tumor samples with several nontumorous tissues from an ovary cancer patient." (PMID 34068254, 2021). "Even though the general population lifetime risk of ovarian cancer is only approximately 1.4%, individuals at high-risk of developing the disease due to harboring a germline BRCA1 and BRCA2 mutation have an average cumulative risk of between 40% to 75% and 11% to 34%, respectively." (PMID 32856862, 2020). "In assessing association of this variant with cancer, of the 15 679 BRCA1 carriers, 7889 and 2369 carriers were affected with breast and ovarian cancers, respectively; of 10 979 BRCA2 carriers, 5605 carriers and 2369 carriers were diagnosed with breast and ovarian cancers, respectively." (PMID 32175645, 2020). "The comprehensive ovarian cancer genomic studies revealed that hypermethylated-BRCA1 ovarian cancer with platinum therapy had a similar prognosis as the intact BRCA cancer, whereas BRCA1/BRCA2-mutated ovarian cancer showed better prognosis than the wild-type cancer." (PMID 32269964, 2020). "Because hRAD52 and BRCA2 play distinct roles in DSB repair, we examined the ability of the RAD52 S346X truncation variant to act as a modifier of susceptibility to breast and ovarian cancers in BRCA1 and BRCA2 mutation carriers." (PMID 32175645, 2020). "Even though ovarian cancer risk is lower with OC use, it stays elevated and timely risk-reducing BSO is recommended at the age of 40 years for BRCA1 and at the age of 45 years for BRCA2 mutation carriers." (PMID 32140806, 2020). "Similarly, ~ 50% cases of high-grade ovarian cancers carry BRCA1 and BRCA2 mutations, causing high-incidence of homologous recombination deficiency (HRD)." (PMID 33087072, 2020). "A total of 52 unrelated women at-risk for HBOC and negative for BRCA1/BRCA2 pathogenic variants were evaluated through a gene panel comprising 14 breast and/or ovarian cancer susceptibility genes." (PMID 33134171, 2020).
ovarian carcinoma (continued). "As we did not have genetic data on variants in the BRCA1/BRCA2 genes predisposing for hereditary breast and ovarian cancer or the CDH1 gene predisposing for hereditary diffuse gastric cancer, we excluded these families from the FCCTX cohort." (PMID 32321466, 2020). "Taken together, the 3326A>T heterozygous mutation of BRCA1 gene and the 1342A>C heterozygous mutation of BRCA2 gene were detected in the confirmed II generation ovarian cancer patients, but none of those in healthy generation II was found." (PMID 32356124, 2020). "About 23% of ovarian cancer cases present a familiar inheritance pattern and are defined as hereditary neoplasms; among them, 65–85% are caused by mutations in BRCA1 and BRCA2 genes, involved in the double-strand DNA breaks (DSBs) repair pathway, that cause 54% of OC lifetime risk increase." (PMID 32512900, 2020). "The ovarian cancer risk is 59–65% for the BRCA1 mutation and 34.5–37% for the BRCA2 mutation." (PMID 32322271, 2020). "However, approximately 81% of ovarian cancers in patients with hereditary breast and ovarian cancer (HBOC) caused by BRCA1/BRCA2 gene variants are reportedly serous adenocarcinoma." (PMID 33300090, 2020). "The Belgian guidelines for managing HBOC do not recommend screening for ovarian cancer in BRCA1 or BRCA2 mutation carriers." (PMID 32655641, 2020). "BRCA1 and BRCA2 are the most incriminated genes in inherited breast/ovarian cancers." (PMID 32025337, 2020). "BRCA1- and BRCA2-associated hereditary breast and ovarian cancer syndrome (HBOC) is characterized by an increased susceptibility to breast and ovarian cancer, and to a lesser extent certain other cancers, especially in individuals with a BRCA2 germline mutation." (PMID 32468491, 2020). "Women with a family history of breast and ovarian cancer have been found to opt for risk reduction surgery, e.g., among BRCA1 and BRCA2 mutation carriers, the majority underwent risk-reducing surgery (salpingo-oophorectomy) after their risk was communicated to them." (PMID 33260928, 2020). "Poly-ADP ribose polymerase (PARP) inhibitors are currently used in the treatment of several cancers carrying mutations in the breast and ovarian cancer susceptibility genes BRCA1 and BRCA2, with many more potential applications under study and in clinical trials." (PMID 32183301, 2020). "Synthetic lethality between PARP inhibition and BRCA1/BRCA2 mutations is well-known and several PARP inhibitors, including Talazoparib, have been approved by FDA as treatments for patients with deleterious germline BRCA-mutated ovarian cancers." (PMID 33339368, 2020). "The lifetime risk of ovarian cancer was different between BRCA1 and BRCA2 mutation carriers." (PMID 32096544, 2020). "Although the BRCA2 gene mutation was not documented, we found that 10.4% of patients with ovarian carcinoma other than mucinous carcinoma carry the BRCA1 gene mutation." (PMID 32856862, 2020). "Furthermore, the lifetime risk for ovarian cancers is about 39–63% in BRCA1 mutation carriers and 11–27% in BRCA2 mutation carriers." (PMID 33198203, 2020). "As compared to previous streamlined studies with BRCA1 and BRCA2 testing in ovarian cancer patients only, in our study, genetic testing was performed using a multi-gene panel approach in patients with a personal history of breast and/or ovarian cancer." (PMID 32028617, 2020). "In a large prospective study of BRCA carriers ascertained through family clinics, the cumulative risk, by age 80, of ovarian cancer in women with pathogenic variants in BRCA1 and BRCA2 was estimated to be 44% (95% confidence interval (CI), 36–53%) and 17% (95% CI, 11–25%), respectively." (PMID 33086730, 2020). "Thus, we next sought to investigate if KAT5 expression impacts survival of BRCA2-mutant ovarian cancer patients by mining survival data and matched genotype and expression data from publicly available datasets." (PMID 33257658, 2020).
ovarian carcinoma (continued). "The level of ovarian cancer risk conferred by these mutations is relatively high, indicating that after BRCA1 and BRCA2, the BRIP1, RAD51C, and RAD51D genes are the most important ovarian cancer risk genes, cumulatively contributing to ~ 2% of ovarian cancer cases." (PMID 32359370, 2020). "However, the BRCA2 gene expression in the NIH-OVCAR3 cells (normalised mRNA expression value = 0.71) was similar to that seen in the 12 ovarian cancer cell lines (normalised mRNA expression value = 0.74)." (PMID 32709004, 2020). "The low CNV load was also evident, but only in BRCA2 related breast and ovarian cancers." (PMID 32164626, 2020). "One of the most dramatic examples of success in this area has been the use of poly-ADP-ribose polymerase (PARP) inhibitors in the treatment of patients with tumours that harbour inactivating mutations in the breast and ovarian cancer susceptibility genes, BRCA1 and BRCA2." (PMID 32183301, 2020). "Similarly, other groups have reported reduced time to results with oncology clinic-based BRCA1 and BRCA2 testing for ovarian cancer patients." (PMID 32028617, 2020). "The loss of BRCA2 and BRCA1 function is frequent in breast and ovarian cancers." (PMID 31632280, 2019). "BRCA1- and BRCA2-deficient high-grade ovarian cancers (HGSOCs) were shown to have increased neoantigen burden, increased immune infiltrates, and higher PD-L1 and PD-1 expression compared to BRCA-proficient ovarian cancers." (PMID 31022191, 2019). "Finally, four patients affected from ovarian cancer carried BRCA1 PVs, while a woman was positive for a deleterious variant in BRCA2 gene." (PMID 31336956, 2019). "This is not ideal given that up to 44% of women with HGSC and a documented BRCA1 or BRCA2 gene mutation do not have a family history of breast/ovarian cancer." (PMID 31061661, 2019). "Of the 29 deceased BRCA2 mutation carriers in the surveillance group, 24% died of BC, 59% of another malignancy—including two deaths due to ovarian cancer and seven due to pancreatic cancer—and 17% died of nonmalignancy-related causes." (PMID 31302855, 2019). "Among women who tested positive for either a BRCA1 or BRCA2 gene mutation, 56% had no previous family history of breast or ovarian cancer." (PMID 31061661, 2019). "One such initiative, Traceback Testing, which is funded by the National Cancer Institute, recommends offering at least BRCA1 and BRCA2 testing to all women diagnosed with ovarian cancer identified through pathology or tumor registries, along with follow-up testing and counseling of family members." (PMID 30832243, 2019). "The classic demonstration of synthetic lethality is the role of poly(ADP-ribose) polymerase inhibitors (PARPi) in cancers in which homologous recombination DNA repair (HRR) is defective (HRD), particularly in breast and ovarian cancers associated with germline BRCA1 and BRCA2 mutations." (PMID 30871186, 2019). "The BRCAPRO model predicts the probability of carrying a BRCA1 or BRCA2 mutation, as determined by the status of breast and ovarian cancer, as well as the ages, of the patient’s first and second-degree relatives, and is guided by the prevalence and penetrance of BRCA1 and BRCA2 mutation in carriers." (PMID 30832243, 2019). "Several studies demonstrated that NGS could be an efficient method for detecting somatic mutations in BRCA1 and BRCA2 genes using DNA from formalin-fixed and paraffin-embedded (FFPE) breast and ovarian cancer tissues." (PMID 31065452, 2019). "The cumulative ovarian cancer risk to age 80 years was 44% for BRCA1 and 17% for BRCA2 carriers." (PMID 30915162, 2019). "The other 4 patients were carriers of pathogenic BRCA2 mutations, with no third-degree relative having been diagnosed with ovarian cancer." (PMID 31263500, 2019).
ovarian carcinoma (continued). "Here, we review genetic testing of high-penetrance hereditary breast and ovarian cancer genes, including BRCA1 and BRCA2, for the purpose of identifying high-risk individuals who would benefit from earlier screening and more sensitive methods such as magnetic resonance imaging." (PMID 30832243, 2019). "More importantly, DMC1 interacts directly with the DNA repair gene BRCA2, which may provide possibilities for synthetic lethality targets for ovarian cancer." (PMID 31572446, 2019). "Associations between short CAG repeats and worse outcomes were also seen in subgroups of patients with or without other risk factors for ovarian cancer, including obesity (BMI ≥25 or <25) or BRCA2 mutation." (PMID 30791431, 2019). "As for other DNA repair genes for which WBC promoter methylation has not been linked to cancer, such as BRCA2, somatic methylation is a rare event in breast as well as ovarian cancer." (PMID 31225507, 2019). "The contribution of BRCA1 and BRCA2 mutations to breast and ovarian cancer incidence has not been well explored in Asian population, where both cancer incidence and mutation prevalence are lower compared to western countries." (PMID 29861850, 2018). "In ovarian cancer, FDA-approved poly ADP-ribose polymerase inhibitors, olaparib and rucaparib, have been used for the treatment of ovarian cancer in patients harboring the BRCA1, BRCA2, and other DNA repair gene mutations and were sensitive to platinum-based chemotherapies." (PMID 29503809, 2018). "In a 72-year-old woman with no associated personal or family history of breast and/or ovarian cancers, we identified a novel somatic pathogenic BRCA2 variant (c.18_28delAGAGAGGCCAA, p.Lys6Asnfs*4) using next-generation sequencing (NGS)." (PMID 29899995, 2018). "The BRCA2 variant, also known as K3326X, was firstly interpreted as pathogenic, but its identification in control populations with no increase in breast or ovarian cancer occurrence led to its reinterpretation of benign polymorphism." (PMID 29346284, 2018). "Based on the findings showing suppression of BRCA2 expression upon MEK inhibition, we sought to investigate whether impaired HR caused by pimasertib in BRCA-proficient ovarian cancer cells would result in increased DNA damage following PARP inhibition." (PMID 29545922, 2018). "Lifetime risks of ovarian cancer were 54% for BRCA1 and 23% for BRCA2 mutation carriers." (PMID 30301218, 2018). "In other tumor types, such as lung and ovarian cancer a high mutational burden has a survival advantage in non-ICI treated patients, but in both instances has been attributed to DNA-repair deficiency primarily via BRCA1, BRCA2, or POLE genes." (PMID 29743104, 2018). "One of the largest case control studies to assess this effect of oral contraceptives found a reduced risk of ovarian cancer in carriers of BRCA1 mutations (odds ratio 0.56 (95% CI 0.45–0.71); p < 0.0001) and carriers of BRCA2 mutations (0.39 (95% CI 0.23–0.66); p = 0.0004)." (PMID 29466291, 2018). "We systematically reviewed the literature and relevant data repositories to characterise the prevalence and spectrum of germline variants in breast and ovarian cancer susceptibility genes in the Indian population, including putative BRCA1 and BRCA2 founder mutations." (PMID 35693198, 2018). "The BRCA2 p.A75P mutation is, however, not classified as predisposing to breast/ovarian cancer by LOVD, or ClinVar." (PMID 29641532, 2018). "Two of the nonsense mutations (p.C675X and p.E1013X) in BRCA1, 7 of the frameshift (p.N1626*11, p.N3024*16, p.Q1429*8, p.L2092*6, p.K1057*7 (x2), and p.F1546*21) in BRCA2 and a single frameshift (p.Q60*6) in PALB2 would predispose the carrier to breast/ovarian cancer." (PMID 29641532, 2018).